CD4 (CD4 molecule)
Diseases named in the same sentence as CD4 in open-access papers (continued):
Sharing a sentence is not in itself a finding about the gene and the disease.
lymphopenia (continued). "Despite lymphopenia, a fixed number of cells were added to the assay, and therefore the ability of adaptive CD8+ and CD4+ T cells to generate IFN-γ-responses, as a frequency per subset, continued to increase during acute infection until ~15 days after disease onset." (PMID 33976217, 2021). "Given that HIV+/aTB+ patients are characterized by low absolute CD4 counts (median: 106 cells/mm3), we hypothesized that the lack of a SARS-CoV-2–specific response could be related to CD4 lymphopenia." (PMID 33945513, 2021). "A Rag-mutant mouse model of human OS exhibits lymphopenia, LIP, and activated CD4+ cells." (PMID 33923792, 2021). "Lymphopenia is not subset-specific within T cells and the numbers of both CD4+ and CD8+ T cells are rapidly reduced during the virus infection." (PMID 34659245, 2021). "Conceivably, serum IL-7 concentration was also inversely related with the number of T cells, CD4+ and CD8+ cells; as a feedback response to the lymphopenia, which would further highlight the relation between lymphopenia and elevated IL-7 levels in SARS-CoV-2 infection." (PMID 34603318, 2021). "Consequently, our investigations have focused on the function of T cells, and in particular CD4+ cells due to the known role of CRACR2A in their activation and also progressive selective CD4+ lymphopenia which was evident from the patient’s phenotype." (PMID 34908525, 2021). "In patients with severe COVID‐19, but not in patients with mild disease, lymphopenia is a common feature, with drastically reduced numbers of CD4+ T cells, CD8+ T cells, B cells and natural killer (NK) cells." (PMID 33082954, 2020). "Higher numbers of PTPN22 KO compared to WT CD4 T cells were recovered from lymph nodes and spleen, further confirming that the influence of PTPN22 on lymphopenia induced T cell proliferation was cell intrinsic and independent of the presence of other PTPN22 KO hematopoietic cells." (PMID 32047502, 2020). "The respiratory distress peaks at 7 to 10 days with manifestations of immune dysregulation, including cytokine release syndrome with elevation of cytokine levels (IL‐6, IL‐8, IL‐1, IL2R, IL‐10, and TNF‐α), lymphopenia (in CD4+ and CD8+ T cells), and decreases in IFN‐γ expression in CD4+ T cells." (PMID 32472653, 2020). "Lymphopenia is severe and constant, with a nadir on day 2 of ICU stay (median 0.555 109/L; interquartile range (IQR) 0.450 109/L); all lymphocytic subgroups are dramatically reduced in critically ill patients, while CD4/CD8 ratio remains normal." (PMID 32605582, 2020). "Lymphopenia-induced proliferation favors expansion of CD8+ memory T cells, because CD8+ memory T cells express higher levels of a component of the IL-15 receptor (CD122) and CD4+ T cell homeostatic expansion is limited by IL-7-dependent STAT-1 activation." (PMID 33013907, 2020). "Lymphopenia in SARS-CoV-2 consists of depletion of both CD4+ and CD8+ T cells with no significant alteration in CD4+/CD8+ ratio." (PMID 32499988, 2020). "CD4+ and CD8+ T cells post Covid-19 were on the whole, less comprised of naïve and memory subsets in survivors vs. healthy donors, while the former had a lesser proportion of naïve cells on a background of lymphopenia." (PMID 33408715, 2020). "The CD4:8 ratio is likely reduced in RRMM patients as a whole as they were probably treated previously with cyclophosphamide (commonly used in induction regimens in Australia), which is known to induce lymphopenia." (PMID 33013907, 2020). "We demonstrated that the observed lymphopenia postinfusion is due to a combined RMD effect, consisting of (i) apoptosis; (ii) downregulation of cell surface markers CD3, CD4, and CD8; (iii) upregulation of homing markers α4β7, CCR7, and CCR9; and (iv) migration from the periphery to the gut and LNs." (PMID 33362765, 2020). "Although the long-term duration of CD4-lymphopenia following RTX therapy is not known, RTX-related CD4-lymphopenia in our patients cannot be ruled out." (PMID 31947836, 2020).
lymphopenia (continued). "CHIKV induced a transient absolute lymphopenia with no clinical consequence, without change of CD4+ and CD8+ T cells proportions, and without any virological impact in treated patients." (PMID 32503031, 2020). "A first study in humans was done in patients with metastatic melanoma and sarcoma and showed the ability of this cytokine to increase the number of CD4+ and CD8+ lymphocytes and decrease in the percentage of CD4+ T-regulatory cells suggesting its role in treating lymphopenia." (PMID 32849527, 2020). "PJP usually develops in patients with CD4+counts below 300/mm3, although the depth of lymphopenia does not correlate with PJP severity." (PMID 31776705, 2019). "Conversely in NHL, altered CD8+ T cell numbers (<200/mm3) correlate with a poor prognosis whereas CD4+ lymphopenia (<500/mm3) does not." (PMID 30922400, 2019). "It was reported that FASLG and TNFSF10 can trigger apoptosis in both CD4+ and CD8+ T cells, which could explain the lymphopenia during ASF infection." (PMID 31725732, 2019). "Cellular immunodeficiency is based on naïve CD4+ and CD8+ T-cell lymphopenia." (PMID 31849966, 2019). "Good’s syndrome (GS), also referred to as thymoma with immunodeficiency, is a rare immunodeficiency syndrome related to thymoma, characterized by hypogammaglobulinemia, low or absent B cells, CD4+ lymphopenia, and reversal of the CD4/CD8 ratio." (PMID 29631544, 2018). "The patient presented with splenomegaly, lymphopenia with low CD4+ and CD8+ T cells as well as NK cells, and was found to have decreased frequency of naive CD4+ T cells and increased CD4+ T-effector memory cells (see Supplementary Note 1 for patient description)." (PMID 29382851, 2018). "Consistently with what was observed in human SARS-CoV patients, lymphopenia was observed in the lungs of both SARS-CoV MA15-infected C57BL/6J and C3–/– mice with reduced percentages of B cells and CD4 T cells relative to those in mock-infected mice following infection." (PMID 30301856, 2018). "Six (4%) patients had combined CD3, CD4, CD8, CD19, and CD56 lymphopenia." (PMID 29371544, 2017). "Importantly, despite the marked naive CD4 T-cell lymphopenia, ∅Thy featured preserved CD31− naive CD4 T-cell counts." (PMID 28154568, 2017). "Our group has previously shown that patients with RRMM have marked CD4+ T lymphopenia that does not recover with lenalidomide/dexamethasone therapy." (PMID 27599546, 2016). "Although some helper CD4+ T cells are known to bolster the cytotoxicity of CD8+ T cells, such as Th1 and Th17 cells, other non-specific CD4+ T cells impair the engraftment of infused CD8+ T cells by competing for cytokines induced by lymphopenia." (PMID 26885368, 2016). "Even though lymphopenia is evident in the secondary lymphoid organs, the phenotype of CD4+ T cells at 4 weeks of age is not dramatically altered." (PMID 27023180, 2016). "Laboratory work-up in all three children was remarkable for CD4 lymphopenia, absence of naïve T cells and hypergammaglobulinemia (yet low IgG2 and poor pneumococcal responses) without evidence of autoimmunity." (PMID 26801501, 2016). "Further immunological investigations included flow cytometric evaluation of lymphocyte subsets which showed a CD4+ T-cell lymphopenia and complete absence of B-cells." (PMID 27576953, 2016). "Unlike the CD4+ T lymphopenia and increased cytokine production seen in RRMM, these changes were also already present in NDMM, in particular within the CD8+ T cell population." (PMID 27599546, 2016). "Similar findings have been demonstrated in experimental animal models and also in healthy individuals under conditions of acutely induced hyperglycaemia, which led not only to lymphopenia but also to a decline of subpopulations of lymphocytes including CD3+, CD4+, and CD8+ T lymphocytes." (PMID 28050566, 2016).
lymphopenia (continued). "We therefore conclude that the CD4+ and B cell lymphopenia measured in the LN, decreased Th1 response of CHIKV-specific CD4+ T cells and the action of TGFβ likely contribute to the total IgG and IgG2c antibody deficiency and to reduced CHIKV-neutralizing titers on day 60 post-infection." (PMID 27736984, 2016). "In regards to abnormal laboratory findings all patients had hypogammaglobulinemia with the majority also displaying low or absent B-cells (87 %), anaemia (85 %) or CD4 + T-cell lymphopenia <360cells/μL (73 %)." (PMID 27576953, 2016). "The dKO component showed accumulation of mature CD4 SP thymocytes and peripheral CD4+ lymphopenia, unlike wild-type competitors, indicating that the effect of Jmjd3 and Utx is cell-intrinsic." (PMID 26328764, 2015). "In human lymphopenia diseases, such as HIV infection, idiopathic CD4+ T lymphopenia, high dose chemotherapy and auto-immune diseases, patients often have increased circulating levels of IL-7 and a strong inverse correlation between the levels of IL-7 and the number of CD4+ T cells." (PMID 25955647, 2015). "In the current study, we analyzed recovery samples of 6 severe patients after clearance of the infection (on average 4 weeks after discharge) and found that the numbers of NK cells as well as CD4+ and CD8+ T cells had returned to normal, indicating that the lymphopenia was transient." (PMID 26162090, 2015). "The fact that PD-1 pathway impedes accumulation of CD4 and CD8 TEM cells during LIP may be important in regulating autoimmunity correlated with lymphopenia settings." (PMID 25803808, 2015). "Idiopathic CD4+ lymphocytopenia (ICL) is a rare syndrome of severe CD4 T cells decrease in the absence of HIV infection or any defined immunodeficiency." (PMID 24799913, 2014). "Thus, chronic exposure to Type-I IFN in the setting of lymphopenia led to enhanced CD8 T cell expansion and impaired CD4 T cell homeostasis." (PMID 24603698, 2014). "Collectively, analyses of T cell recovery in multiple sites indicate that T cell lymphopenia is not a consistent feature of ageing: T cell lymphopenia was essentially restricted to the CD4 subset in some secondary lymphoid organs." (PMID 24829607, 2014). "To understand the mechanisms by which HIV infection alters the homeostasis of CD4 and CD8 T cell pools, we hypothesized that lymphopenia and the chronic exposure to IFN-α may both play a role in this dysregulation." (PMID 24603698, 2014). "This was characterized by lower CD4+ T-cell cytokine-production capacities and lymphopenia, but not by increased percentage of regulatory T cells." (PMID 25005517, 2014). "One further patient with recurrent infections and CD4 lymphopenia, but without lymphoproliferation was just recently discovered." (PMID 25339095, 2014). "Altogether these findings suggest that during HIV infection, the interplay of lymphopenia and inflammation (Type-I IFN) may lead to alterations in the ways that CD4 and CD8 T cells respond to stimulation with Type-I IFNs." (PMID 24603698, 2014). "In addition, CD4+ T cells that survive cytoreductive chemotherapy and harbor HIV-1 DNA are likely to proliferate in response to chemotherapy-induced lymphopenia through IL-7 mediated homoestatic proliferation." (PMID 24638072, 2014). "Using this protocol, we were able to induce a CD4 lymphopenia similar to that observed in BNm rats, in terms of number and phenotype of CD4 T cells (data not shown)." (PMID 22275874, 2012). "Negative tuberculin skin test, lymphopenia, and the low CD4+ T cell count indicated that our patients had defects in cellular immunity, which lead to the HPV infection." (PMID 22524894, 2012). "During measles there is no deficit in production of CD4+ or CD8+ SP thymic emigrants, suggesting that a decrease in thymic output is not the cause of lymphopenia or depressed cellular immunity." (PMID 23029357, 2012). "There was both CD4+ T cell and CD19+ B cell lymphopenia present." (PMID 21477322, 2011).
lymphopenia (continued). "In spite of the observed peripheral lymphopenia, central (CD44highCD62Lhigh) and effector (CD44highCD62Llow) memory cells were equally represented among CD4+ and CD8+ (data not shown) T cells derived from Rac1N/Rac3KO and Rac3KO littermates." (PMID 21469092, 2011). "Taken together, our results show that CD40L blockade has an unsuspected effect on the lymphopenia-induced proliferation of donor CD4+ T cells but does not prevent their ability to promote the CD8+ T cell-mediated onset of disease." (PMID 20856822, 2010). "Lymphopenia is common in H5N1 patients and low CD3 counts and CD4:CD8 ratios have been reported." (PMID 20540811, 2010). "Since lymphopenia is induced by irradiation in our model, activation of the cross-presenting APCs could by-pass the need for CD40 engagement by CD4+ T helpers." (PMID 20856822, 2010). "This is in apparent contradiction with a previous study showing that CD40L co-stimulation did not play a role in lymphopenia-induced proliferation of CD4+ T cells in irradiated hosts." (PMID 20856822, 2010). "Moreover, a study noted that docetaxel-based chemotherapy is related to non-neutropenic infections, partly due to CD4+ lymphopenia." (PMID 41245139, 2025). "The proband, identified during family follow-up, had recurrent mucocutaneous infections, marked CD4+ lymphopenia with CD4/CD8 inversion, and near-absent HLA-DR on B cells; he was started on monthly intravenous immunoglobulin and trimethoprim–sulfamethoxazole prophylaxis." (PMID 41376631, 2025). "Laboratory investigations revealed profound CD4+ lymphopenia and negative HIV serology." (PMID 40786310, 2025). "Increased expression of TIGIT on CD4 and CD8 cells observed in our IPF cohort may suggest recruitment of T cells from peripheral blood (this explains the peripheral lymphopenia of IPF patients) to the lung interstitium, as described in the histopathological features of IPF." (PMID 38540243, 2024). "Considering that the lack of CD2BP2/U5–52K induces T cell lymphopenia in both spleen and lymph nodes, we wondered whether the ratio between naïve and memory T cells in both CD4+ and CD8+ populations is affected in the absence of CD2BP2/U5–52K." (PMID 39308865, 2024). "However, an induced period of peripheral lymphopenia in CD4+ CD25+ depleted animals did not, on its own, affect disease onset, suggesting the involvement of other mechanisms in disease initiation." (PMID 38404584, 2024). "Although there was no lymphopenia, cryptococcal infection developed as a consequence of the CD4 counts, which may have been low." (PMID 39512980, 2024). "With respect to the T cell compartment, PD-1 expression on CD4+ and CD8+ T cells is quickly upregulated during T cell activation and exhaustion, including HIV-specific T cells, in the presence of proinflammatory cytokines as well as in homeostatic T cell proliferation during lymphopenia." (PMID 38557496, 2024). "In addition to foreign antigen–specific memory Th cells, murine studies have identified memory phenotype CD4+ T cells, which arise in response to interactions with self-peptide MHC in combination with homeostatic cytokines in the setting of lymphopenia-induced proliferation." (PMID 37856221, 2023). "Thus, while lymphopenia in dTg mice affected the total CD4 T cell population in the colon, this did not extend to Treg." (PMID 36690619, 2023). "It is likely his inability to suppress the attenuated varicella strain was related to his profound CD8 lymphopenia rather than the CD4 lymphopenia, though this could not be confirmed as both were significantly decreased." (PMID 36648576, 2023). "However, no significant impact of lymphopenia and CD4+ T-cell lymphopenia on disease severity was found." (PMID 36678457, 2023). "Immuno-suppressive marker tests such as total immunoglobulin levels or CD4 counts were not performed because lymphocytopenia may result into suboptimal results, which could not be used in clinical management." (PMID 35632677, 2022).
lymphopenia (continued). "Another limit of this study is the absence of information on treatments received by patients so that their link between CD4+ T lymphopenia could not be addressed." (PMID 35546670, 2022). "IL-33 stimulation of CD4+ T cells was not required for lymphopenia-induced expansion, however." (PMID 35503257, 2022). "Along this line, we recently showed that chronic HCV infected individuals with cirrhosis displayed a greater magnitude of naïve CD4+ lymphopenia and effector/memory CD4+ and CD8+ Tell activation when compared to their non-cirrhotic counterparts even after effective DAA therapy." (PMID 35062255, 2021). "Furthermore, we investigate telomere length and telomerase activity in CD4+ and CD8+ lymphocytes to evaluate whether excessive proliferative pressure or inadequate telomeric maintenance may account for the observed lymphopenia in septic shock patients." (PMID 32825352, 2020). "Features such as a reduced CD4:8, low proportions of circulating TN and high proportions of TEM/TEMRA indicate immunosenescence and shifts in the T cell population due to iatrogenic lymphopenia, and are likely to correlate with poorer responses to immunotherapeutics." (PMID 31093282, 2019). "When compared to HCs, KTRs presented global lymphopenia (median: KTRs = 1,256 vs. HCs = 1,996/mm3; P = 0.0455), involving mainly B cells (median CD19+: KTRs = 45 vs. HCs = 213/mm3, P = 0.0002) and CD4+ T cells (median CD4+: KTRs = 484 vs. HCs = 1,007/mm3; P = 0.0007)." (PMID 31639143, 2019). "They revealed significant abnormalities including lymphocytopenia notably characterized by decreased counts of B cells, naïve CD4+ and CD8+ T cells, NK cells, MAIT and absence of iNKT cells, and impaired T‐cell proliferation in response to PHA, OKT3, and Tetanus toxoid." (PMID 29282224, 2018). "While a notable difference between these two settings of CD4 lymphopenia and HIV-1/SIV infection is the lack of an infectious component, these data may shed novel insights into ILC biology, and offer striking parallels to ILC dynamics in HIV-1/SIV infection." (PMID 30262807, 2018). "GS is typically detected based on a diagnosis of thymoma in combination with characteristic clinical laboratory test results, such as a low number or even absence of peripheral B cells, hypogammaglobulinemia, CD4+ T lymphopenia, and an inverted ratio of CD4+/CD8+ cells." (PMID 29850635, 2018). "Therefore, our analysis provides no strong evidence that lymphopenia-induced proliferation through reduced competition for homeostatic stimuli is a dominant factor in establishing the naive CD4 and CD8 T-cell pools early in life." (PMID 29641514, 2018). "Lymphopenia-induced proliferation of a high number of enriched CD4+CD25− T cells, an inoculum depleted of the major non-T cell populations as well as CD8+ and gamma-delta T cells, gave rise to colon disease as severe as that observed in hosts receiving the low number of CD4+CD25− T cells." (PMID 27353032, 2016). "Importantly, a reversed CD4:CD8 ratio was often a result of CD4 lymphopenia without dramatic alteration in the absolute CD8+ T cell count." (PMID 27481850, 2016). "One may consider that redistribution of CD4 T cells rather than T cell lymphopenia is the crucial phenomena occurring during ageing." (PMID 24829607, 2014). "Thus we confirmed in a different strain model that T cell lymphopenia developing in lymphoid organs was not recapitulated in GALT and even associated to CD4 T cell accumulation at some sites." (PMID 24829607, 2014). "To confirm that the observed impairment of virus control in CIITA−/− mice was indeed caused by CD4+ T cell-lymphopenia and not by some other effect mediated by CIITA deficiency, we infected wild-type C57BL/6 mice that had been depleted of CD4+ T cells with anti-CD4 antibody (GK1.5)." (PMID 24466045, 2014).